ELAC2 (elaC ribonuclease Z 2)
Diseases named in the same sentence as ELAC2 in open-access papers (continued):
Sharing a sentence is not in itself a finding about the gene and the disease.
hypertrophic cardiomyopathy (9 papers, 2018 to 2025). A condition in which the myocardium is hypertrophied without an obvious cause. "It appears that the hearts of gZHCM flies combine features of both hypertrophic and dilated cardiomyopathy, reminiscent of the dilated stage of hypertrophic cardiomyopathy (D-HCM) reported for some patients with ELAC2 mutations." (PMID 34338278, 2021). "Here, we report the identification of 16 novel ELAC2 variants in individuals presenting with mitochondrial respiratory chain deficiency, hypertrophic cardiomyopathy (HCM), and lactic acidosis." (PMID 31045291, 2019). "In our previous work, we investigated the functional consequences of ELAC2 variants in patients presenting with a recessively inherited form of hypertrophic cardiomyopathy (HCM), hypotonia, lactic acidosis, and failure to thrive." (PMID 31045291, 2019). "In addition, mutation in ELAC2 leads to shortage of oxidative phosphorylation [COXPD17] 17 which is a recessive autosomal rare disorder of mitochondrial operation established by intensive hypertrophic cardiomyopathy." (PMID 32592348, 2020). "Although pathogenic biallelic ELAC2 mutations in patients are associated with psychomotor delay, hypotonia, and hypertrophic cardiomyopathy, it is not clear which phenotypes are driven by mitochondrial dysfunction or defects in maintaining specific nuclear tRNA isoacceptor pools." (PMID 41237252, 2025).
cardiomyopathy (7 papers, 2016 to 2025). A disease of the heart muscle or myocardium proper. "Cardiomyopathy-associated mutations in ELAC2 resulted in tRNA processing defects and impaired translation." (PMID 41264253, 2025). "Mutations in ELAC2 cause severe cardiomyopathies and premature death in infancy as a consequence of disrupted mitochondrial tRNA cleavage that leads to reduced OXPHOS function." (PMID 37093546, 2023). "To date, twenty autosomal recessive variants in the ELAC2 gene have been linked to MD, most commonly presenting with cardiomyopathy, developmental delay and lactic acidosis." (PMID 36836802, 2023). "Mutations in ELAC2 or deletion of the mouse Elac2 in the heart lead to cardiomyopathies due impaired 3′ tRNA processing that causes loss of mature tRNAs required for translation, consequently resulting in protein synthesis defects and energy dysfunction." (PMID 37093546, 2023). "Variants in the ELAC2 gene have been predominantly linked to severe to mild cardiomyopathy that, in its milder forms, is accompanied by variably severe neurological presentations." (PMID 36836802, 2023). "Patients diagnosed with cardiomyopathy due to mutations in ELAC2 have a median life expectancy of 4 months." (PMID 34338278, 2021). "Recently the ELAC2 gene was added to the list of those associated with cardiomyopathy." (PMID 37228086, 2023). "The role of ELAC2 in processing nuclear and mitochondrial tRNAs at their 3′ ends is nonredundant, as its heart and skeletal muscle‐specific loss in mice causes profound cardiomyopathy and premature death at 3 weeks of age." (PMID 37093546, 2023). "Our study expands the genetic spectrum of ELAC2-linked disease and suggests that cardiomyopathy is not an invariably present clinical hallmark of this pathology." (PMID 36836802, 2023). "Our report expands the genetic spectrum of ELAC2-linked MDin humans and substantiates previous findings that ELAC2 mutations do not always present with cardiomyopathy." (PMID 36836802, 2023). "In conclusion, our study expands the genetic spectrum of ELAC2-linked disease and suggests that cardiomyopathy is not an invariably present clinical hallmark of this pathology." (PMID 36836802, 2023). "This case demonstrates that ELAC2 mutations are not exclusively confined to a lethal pediatric cardiomyopathy but can also be associated with symptoms and laboratory findings suggestive of a neuroacanthocytosis syndrome." (PMID 30217939, 2018). "Patients carrying ELAC2 variants commonly present cardiomyopathies that can be severe infantile cardiomyopathies—dilated and/or hypertrophic—often with a negative prognosis or milder cardiomyopathies, which are associated with prolonged survival." (PMID 36836802, 2023). "Therefore, we propose that patients with neurological presentations, in the absence of cardiomyopathy, should also be suspected of carrying ELAC2 mutations." (PMID 36836802, 2023). "Therefore, pathogenic ELAC2 variants should be considered as a plausible cause of mitochondrial disease in patients with neurological presentations regardless of the presence of cardiomyopathy." (PMID 36836802, 2023). "Mice lacking ELAC2 or mitochondrial RNase P in the heart have a short life span and die with profound cardiomyopathy." (PMID 37228086, 2023). "In conclusion, the absence of significant cardiomyopathy and the presence of moderately severe intellectual disability as the main feature in this family suggest that aberrations in ELAC2 should be considered in children with intellectual disability as the sole presenting feature." (PMID 27769300, 2016).
cardiac hypertrophy (3 papers, 2017 to 2021). "Some studies that describe CM cases associated with ELAC2, have proposed incomplete processing of mitochondrial transcripts as the cause of organelle malfunction that, in turn, leads to heart hypertrophy." (PMID 34338278, 2021). "In humans, multiple mutations of ELAC2 have been associated with the early onset of cardiac hypertrophy and decompensation, although the causal connection between mutant ELAC2 forms and CM has not been explicitly established." (PMID 34338278, 2021). "Furthermore, mutations in the human ELAC2 gene is associated with mt-tRNA processing defects associated with cardiac hypertrophy." (PMID 33041815, 2020). "A few studies suggest that ELAC2 is implicated in mitochondrial disorders and cardiac hypertrophy." (PMID 33041815, 2020). "Also noteworthy in this regard, the conservative substitution Leu423Phe in H. sapiens tRNase ZL (ELAC2) associated with mitochondrially based cardiac hypertrophy is located at the start of β15." (PMID 29045449, 2017). "Consequently, it would be interesting to determine the following: 1) ELAC2 function in mitochondria during compensation and decompensation, 2) ELAC2 levels in hypertrophic hearts, and 3) the functional role of these tsRNAs in cardiac hypertrophy." (PMID 33041815, 2020).
infantile hypertrophic cardiomyopathy (3 papers, 2015 to 2020). "Pathological variants in ELAC2 have been shown to give rise to infantile hypertrophic cardiomyopathy, global developmental delay, and early death." (PMID 33426505, 2020). "The only three previously reported families with defects in ELAC2 gene exhibited infantile hypertrophic cardiomyopathy and complex I deficiency." (PMID 27769300, 2016).
acanthocytosis (2 papers, 2018 to 2021). "We describe a patient with a complex hyperkinetic syndrome and acanthocytosis, harboring biallelic ELAC2 mutations." (PMID 30217939, 2018). "“Familial acanthocytosis with paroxysmal exertion-induced dyskinesias and epilepsy” was later found to be caused by a GLUT1 mutation; acanthocytes have additionally been reported in a variety of neurogenetic disorders, e.g. with mutations of ELAC2 or in aceruloplasminemia." (PMID 33510935, 2021).
hereditary prostate cancer (2 papers, 2015 to 2020). "The coding region of ELAC2 consists of 826 amino acids of a metal dependency hydrolase, and this gene is the susceptibility gene for familial hereditary prostate cancer." (PMID 26241669, 2015).
Intellectual disability (2 papers, 2016 to 2019). "In addition, ELAC2 mutations should be considered when evaluating patient with mainly intellectual disability phenotypes." (PMID 27769300, 2016). "Interestingly, five patients from a consanguineous Arabic family harboring another homozygous ELAC2 mutation involving the same consensus splice site (homozygous c.1423 + 2 T>A) predominantly presented with intellectual disability without prominent cardiac involvement." (PMID 31045291, 2019).
lactic acidosis (2 papers, 2019 to 2024). Metabolic acidosis characterized by the accumulation of lactate in the body. "The consequence of perturbed ELAC2 function is manifested by multiple mitochondrial respiratory chain deficiencies, HCM, and lactic acidosis." (PMID 31045291, 2019). "In the present work, we report the identification of 16 additional ELAC2 variants (ten missense, two frameshift, and four splice mutations) in individuals who present with mitochondrial respiratory chain deficiency, HCM, and lactic acidosis." (PMID 31045291, 2019). "Moreover, it indicates a strong relationship between a confirmed molecular diagnosis of ELAC2‐related mitochondrial disease and the key clinical phenotypes (HCM, multiple respiratory chain defects, and lactic acidosis) for the majority of variants detected." (PMID 31045291, 2019).
very long chain acyl-CoA dehydrogenase deficiency (2 papers, 2023 to 2024). An inherited disorder of mitochondrial long-chain fatty acid oxidation with a variable presentation including: cardiomyopathy, hypoketotic hypoglycemia, liver disease, exercise intolerance and rhabdomyolysis. "In our cohort, the most prevalent genetic abnormalities identified were ELAC2 mutations and very long-chain acyl-CoA dehydrogenase deficiency (VLCADD)." (PMID 38568384, 2024). "The most common genetic abnormality was familial infantile hypertrophic CM caused by the gene ELAC2 in 19 (23.5%) cases, followed by very long-chain acyl-CoA dehydrogenase deficiency gene defect (VLCAD) in 17 (21%) cases." (PMID 38249165, 2023).
encephalomyopathies (1 paper, 2016). "The group of ELAC2-related encephalomyopathies is a recent addition to the rapidly growing heterogeneous mitochondrial disorders." (PMID 27769300, 2016).
epithelial ovarian cancers (1 paper, 2016). "Comparing histologic subtypes of epithelial ovarian cancers, ELAC2 and CYB5R3 mRNA levels were significantly lower in HGSOC than in non-HGSOC (p<0.0001, p=0.03, respectively)." (PMID 27323405, 2016). "In summary, altered ABHD2, ELAC2 and CYB5R3 mRNA expression was identified through our functional genomics screen and was significantly reduced in ovarian cancer, especially in HGSOC, relative to that in SBT or normal ovarian epithelium." (PMID 27323405, 2016). "Like ABHD2, ELAC2 and CYB5R3 mRNA levels were significantly lower in ovarian cancer than in SBT (p=0.008 and 0.003, respectively)." (PMID 27323405, 2016).
lung diseases (1 paper, 2022). "For the majority of genes such as Elac2, Csnk1a1, Eif3a, Eif4g2, Tmed2 and Mpv17l, a role in the pathogenesis of lung diseases was indicated by previous studies, although their functions in the neonatal lung remain unexplored." (PMID 36271035, 2022).
cancer (13 papers, 2010 to 2024). A tumor composed of atypical neoplastic, often pleomorphic cells that invade other tissues. "In ERG positive cancers only high Gleason grade (p< 0.0001) remained as significantly linked to ELAC2 expression." (PMID 31452838, 2019). "The p.Ala541Thr and p.Arg781His ELAC2 substitutions were first characterized as variants in a pedigree in Utah displaying early‐onset prostate and other cancers." (PMID 31045291, 2019). "The observed up-regulation of nuclear ELAC2 expression in the subset of ERG positive cancers might be caused by a general up-regulation of the TGF-ß pathway as a consequence of ERG fusion." (PMID 31452838, 2019). "For example, moderate or strong nuclear ELAC2 staining was seen in 48.1% of cancers with TMPRSS2:ERG fusion detected by FISH but in only 31.6% of cancers without such rearrangement (p< 0.0001)." (PMID 31452838, 2019). "It is a limitation of our study that only one single 0.6 mm tissue spot per patient was analyzed, making it possible that the fraction of ELAC2 positive cancers was underestimated in case of tumor heterogeneity." (PMID 31452838, 2019). "It showed that ELAC2 staining in cancer glands was typically stronger as compared to adjacent normal prostatic glands." (PMID 31452838, 2019). "That fractions of ELAC2 positive cancers were somewhat higher in PTEN and 3p deleted cancers likely reflects this association." (PMID 31452838, 2019). "Recent studies have shown that ELAC2 is involved in the generation of MALAT1, a cancer-associated long noncoding RNA which participates in regulation of pre-mRNA splicing, tRNA-derived small RNAs, and viral microRNAs (miRNAs)." (PMID 21781332, 2011). "In cancer, their biogenesis is controlled by a tRNA 3’-endonuclease ELAC2." (PMID 33604354, 2020). "ELAC2 expression in cancer was also lower than that in normal ovarian epithelium (p=0.005)." (PMID 27323405, 2016). "The difference in 1-, 5- and 10-year recurrence-free survival between strong and weak nuclear ELAC2 intensity is 7.2/13.8/17.6% in all cancers, 7.4/16.1/26.5% in the ERG negative subset, and 3.1/5.7/9.8% in the ERG positive subset." (PMID 31452838, 2019). "The average Ki67LI increased from 2.02 in cancers lacking nuclear ELAC2 expression to 4.18 in cancers with high ELAC2 levels (p< 0.0001)." (PMID 31452838, 2019). "The in 1-, 5- and 10-year recurrence-free survival differed between strong and weak nuclear ELAC2 intensity levels by 7.2 /13.8/17.6% in all cancers, 7.4/16.1/26.5% in the ERG negative subset and 3.1/5.7/9.8% in the ERG positive subset." (PMID 31452838, 2019). "Of note, finding frequent overexpression of ELAC2 in our cancers does not exclude a tumor suppressive function." (PMID 31452838, 2019). "Additionally, ELAC2 exhibits non-tRNA target cleavage, exemplified by its processing of MALAT1, a long noncoding RNA implicated in many cancers." (PMID 38826313, 2024). "Similarly, some progressors (CHMP4B, CSTF1, and LSM14B) and suppressors RBPs (ATP5F1A, GTF2E2, RTF1, ELAC2, LRRC47, and MRM3) have never been associated with COAD or READ, but present oncogenic properties in other cancer types." (PMID 37384253, 2023).
mitochondrial disease (7 papers, 2015 to 2025). "Mutations in ELAC2 are coupled to many clinically relevant mitochondrial diseases, with patient symptoms ranging from pediatric cardiomyopathy to adult intellectual disability depending on their functional severity." (PMID 39516281, 2024). "This study reveals its complete structural framework, detailing its role in tRNA maturation and substrate recognition, and provides insights into mitochondrial disease mechanisms linked to mutations in its catalytic subunit ELAC2." (PMID 39516281, 2024). "Mutations in ELAC2 have been associated with mitochondrial disease in five individuals suffering from an infantile-onset hypertrophic cardiomyopathy and complex I deficiency." (PMID 25806043, 2015). "Clinical studies have associated mutant alleles of ELAC2/RNase ZL with mitochondrial disease." (PMID 41183022, 2025). "Furthermore, our study links mutations in ELAC2 to clinically relevant mitochondrial diseases, offering a deeper understanding of the molecular defects contributing to these conditions." (PMID 39516281, 2024). "In addition to being implicated in mitochondrial disease, ELAC2 is also an established susceptibility gene for prostate cancer." (PMID 25806043, 2015).
tumor (5 papers, 2014 to 2023). "Increased nuclear ELAC2 expression was linked to high Gleason grade (p< 0.0001), higher pathological tumor stage (p< 0.0001) and positive nodal status (p = 0.0003)." (PMID 31452838, 2019). "Strong nuclear ELAC2 expression was associated with advanced tumor stage, nodal metastasis, higher Gleason grade, presence of TMPRSS2:ERG fusion, higher Ki67-labeling index and PTEN deletion." (PMID 31452838, 2019). "Nuclear ELAC2 overexpression is associated with adverse tumor phenotype in our study (advanced pT stage, high Gleason grade, lymph node metastases, and early biochemical recurrence, p < 0.0001 each)." (PMID 31452838, 2019). "We found variants in the five genes APC, BRCA1, RET, RNASEL, and STK11 that were linked to autosomal dominant forms of cancer or neoplasm as well as four complex risk variants in ELAC2, MSR1, AIP, and SDHB." (PMID 25333069, 2014). "In line with our findings, tumor cell staining with prominent nuclear localization is also shown in “The human protein atlas” for the anti-ELAC2 antibody HPA019535." (PMID 31452838, 2019). "Possible explanations include that tumor suppressors such as p16, and potentially ELAC2 as well, become up-regulated during tumor progression in an attempt to regain cell cycle control in response to deregulated growth signaling by other causes." (PMID 31452838, 2019). "Overall, the data suggest that tumor relevant functions of ELAC2 and other proteins might be modulated by the ERG fusion status." (PMID 31452838, 2019). "The reasons for tumor associated ELAC2 up-regulation are not known." (PMID 31452838, 2019).
prostate (4 papers, 2005 to 2025). "YL03-47 was transformed with an array of ELAC2 constructs (full length ELAC2, FLAG tagged ELAC2, N-domain ELAC2, C-domain ELAC2, and four full length ELAC2 variants found in prostate patients)." (PMID 15892892, 2005). "We revealed two Tier 2 genes (NOA1 and ELAC2) and one Tier 3 gene (ACAT1) for BPH, two Tier 3 genes (TRMU and SFXN5) for prostatitis, and six Tier 3 genes (MRPL24, NDUFS6, PUS1, NBR1, GLOD4, and PCBD2) for PCa." (PMID 40919435, 2025). "Our analysis revealed two Tier 2 genes (NOA1 and ELAC2) for BPH, two Tier 3 genes (TRMU and SFXN5) for prostatitis, and six Tier 3 genes (MRPL24, NDUFS6, PUS1, NBR1, GLOD4, and PCBD2) for PCa." (PMID 40919435, 2025).
metabolic disorder (1 paper, 2024). "The confirmation of genetic and/or metabolic disorders occurred in 49 patients (21.4%), with VLCAD deficiency identified in 16 patients (7%) and an ELAC2 gene defect in ten patients (4.4%)." (PMID 38568384, 2024). "The genetic and or metabolic disorder was confirmed in 21.4% of patients, most commonly VLCAD defect (16, 7%) and ELAC2 gene defect (10, 4.4%)." (PMID 38568384, 2024).
neurodevelopmental disorder (1 paper, 2022). A behavioral and cognitive disorder with onset during the developmental period that involves impaired or aberrant development of intellectual, motor, or social functions. "Five of these genes are already classified as diagnostic grade genes in the IEM panel (COQ4, ELAC2, MRPL44, MSTO1 and SKIV2L) and three others are diagnostic grade genes in different neurology and neurodevelopmental disorder gene panels (EIF2B4, ELP1, EXOSC8)." (PMID 36229886, 2022).
ELAC2 also shares sentences with these, for which no sentence is quoted: breast carcinoma (3 papers); developmental delay (2); prostate hyperplasia (2); psychosis (2); aceruloplasminemia (1); adenocarcinoma of the (1); adenoma (1); Alstrom syndrome (1); autosomal recessive disease (1); carnitine deficiency (1); Chorea (1); colonic adenomas (1); diabetes (1); dilated cardiomyopathy (1); epilepsy (1); familial dilated cardiomyopathy (1); hereditary hemorrhagic telangiectasia (1); hereditary non-polyposis colorectal cancer (1); hyperplasia (1); ichthyosiform erythroderma (1); liver cancer (1); long QT syndrome (1); lung carcinoma (1); Marfan syndrome (1); McLeod syndrome (1); MELAS (1); microcephaly (1); mood disorder (1); movement disorder (1); mucopolysaccharidosis (1).
A further 9 diseases each share a sentence with ELAC2 in 1 paper.